LRRTM4 (leucine rich repeat transmembrane neuronal 4)
Description:
May play a role in the development and maintenance of the vertebrate nervous system. Exhibits strong synaptogenic activity, restricted to excitatory presynaptic differentiation (By similarity).
Synonyms: FLJ12568
Tractability: Antibody: UniProt places it where antibodies can reach, with medium confidence; UniProt predicts a signal peptide or a membrane-spanning region; its Gene Ontology location is reachable by antibodies, with medium confidence. PROTAC: its protein half-life has been measured.
Gene: Protein-coding gene on chromosome 2 (76,747,685 to 77,593,319, reverse strand). Ensembl gene ENSG00000176204.
Subcellular location: Cell membrane; Postsynaptic cell membrane
Pathways (Reactome):
Neuronal System: Neurexins and neuroligins
Gene Ontology:
Molecular function: signaling receptor activity
Biological process: positive regulation of synapse assembly
Cellular component: plasma membrane; postsynaptic membrane; synapse
Genetic constraint (gnomAD): Loss-of-function variants: 25 observed, 50.36 expected, observed/expected ratio (o/e) 0.5, 90% interval 0.36 to 0.69. The upper end of that interval is the gene's LOEUF score, 0.69, which puts it in group 2 of 6, group 1 being the genes least tolerant of losing a copy. Missense variants: 638 observed, 747.39 expected, observed/expected ratio (o/e) 0.85, 90% interval 0.8 to 0.91. Synonymous variants: 311 observed, 285.53 expected, observed/expected ratio (o/e) 1.09, 90% interval 0.99 to 1.2.
Homologues: Orthologues: chimpanzee LRRTM4 (100% identical), rabbit LRRTM4 (97% identical), guinea pig LRRTM4 (97% identical), dog LRRTM4 (96% identical), pig LRRTM4 (95% identical), mouse Lrrtm4 (95% identical), macaque LRRTM4 (90% identical), rat Lrrtm4 (85% identical), tropical clawed frog lrrtm4 (80% identical), zebrafish LRRTM4 (61% identical), zebrafish LRRTM4 (60% identical), zebrafish lrrtm4l2 (50% identical), and 1 more. Paralogues in human: LRRTM3 (58% identical), LRRTM1 (39% identical), FLRT2 (19% identical), FLRT3 (19% identical), LRRC4C (19% identical), FLRT1 (18% identical), LRRC4 (18% identical), LRRC4B (18% identical), NYX (18% identical), LRRC15 (17% identical), RTN4R (17% identical), PODNL1 (17% identical), and 10 more.
Diseases named in the same sentence as LRRTM4 in open-access papers:
LRRTM4 is named in the same sentence as 25 diseases in open-access papers, as found by Europe PMC text mining. Sharing a sentence is not in itself a finding about the gene and the disease. The quoted sentences say what the papers report.
Anxiety (2 papers, 2021 to 2025). Intense feelings of nervousness, tension, or panic often arise in response to interpersonal stresses. "In a translational view, the findings of enhanced anxiety fit well with reported comorbidities of diseases that have already been linked to LRRTM4, including ASD and Tourette." (PMID 40183503, 2025). "In a translational view, it would be interesting to further characterize the potential of LRRTM4 as a treatment target to ameliorate excessive aggression or anxiety associated with a number of neuropsychiatric conditions." (PMID 40183503, 2025). "Targeting LRRTM4 therapeutically may thus be an interesting novel approach to alleviate excessive aggression or anxiety associated with a number of neuropsychiatric conditions." (PMID 40183503, 2025). "GWEIS identified multiple candidate loci, such as rs114086183 (p = 4.11 × 10−8, LRRTM4) for self-reported depression status and rs149760119 (p = 3.88 × 10−8, GNB5) for self-reported anxiety status." (PMID 34684344, 2021). "Therefore, we performed GWEIS and identified multiple candidate genes interacting with VD, which are implicated in the brain or neural regulation and pathology, such as LRRTM4 for depression status and GNB5 for anxiety status." (PMID 34684344, 2021).
epilepsy (2 papers, 2024 to 2025). A brain disorder characterized by episodes of abnormally increased neuronal discharge resulting in transient episodes of sensory or motor neurological dysfunction, or psychic dysfunction. "Likewise, the LRRTM4 (leucine rich repeat transmembrane neuronal 4) (2p12) gene is associated with schizophrenia and epilepsy and involved in glutamatergic synapses, regulation of synapse assembly, and presynaptic membrane organization." (PMID 40631452, 2025).
Tourette syndrome (2 papers, 2021 to 2025). A neurologic disorder caused by defective metabolism of the neurotransmitters in the brain. "Copy number variations near the LRRTM4 locus, cell‐type specific LRRTM4 enrichment, as well as a duplication of the terminal LRRTM4 exon have been linked to autistic traits, autism spectrum disorder, and Tourette syndrome." (PMID 40183503, 2025). "The duplication breakpoints identified in the Tourette syndrome family reported in this study were also localised near conserved non-coding regions on either side of the terminal exon of LRRTM4." (PMID 35052406, 2021).
anxiety disorder (1 paper, 2025). A category of psychiatric disorders which are characterized by anxious feelings or fear often accompanied by physical symptoms associated with anxiety. "LRRTM4 has not come up as a significant hit in GWAS investigating anxiety disorders directly so far, which may be related to the large heterogeneity of anxiety disorders raising the question of whether specific subforms of anxiety disorders are associated with LRRTM4 dysfunction." (PMID 40183503, 2025). "It will also be interesting to investigate in future studies whether ASD or Tourette patients with and without anxiety disorders show differences in the genetic makeup of the LRRTM4 locus." (PMID 40183503, 2025).
Ascites (1 paper, 2022). Accumulation of fluid in the peritoneal cavity (between the layers of the peritoneum that lines the abdomen). "Selection based on SNPs in the carboxypeptidase Q (CPQ, Gga2) and leucine rich repeat transmembrane neuronal 4 (LRRTM4, Gga22) gene regions resulted in a sex- and simulated altitude- dependent reduction of ascites incidence in two F2 cohorts of the MAS line." (PMID 35090566, 2022). "Therefore, the current study reports on whether MAS based on SNP genotypes for the regions of both CPQ and LRRTM4 can produce offspring with greater innate ascites resistance." (PMID 35090566, 2022).
cerebrovascular disease (1 paper, 2022). "Although the mechanism is unclear, LRRTM4 gene has been associated with cerebrovascular disease in past studies." (PMID 35994481, 2022).
coronary heart disease (1 paper, 2020). "NCBI PheGenI associates the human LRRTM4 gene region with traits such as antihypertension, carotid artery disease, coronary heart disease, and pulmonary embolism, supporting a probable association with AS in broilers." (PMID 32434464, 2020).
depression (1 paper, 2021). "For self-reported depression status, GWEIS identified a significant gene × VD PRS interaction (p < 5.0 × 10−8) at the LRRTM4 gene (rs114086183, p = 4.11 × 10−8)." (PMID 34684344, 2021).
leprosy (1 paper, 2022). Leprosy is a chronic infectious disease affecting primarily the skin and peripheral nervous system. "We also described a molecular signature associated with neural damage in early stages of pure neural leprosy from patients (i.e., HLA-DRB1, MAPK14, GAP43, FABP7, NTN1, and LRRTM4)." (PMID 35492305, 2022).
type 2 diabetes (1 paper, 2024). "While there is no direct evidence linking dietary soy, LRRTM4, or GFPT2 with type 2 diabetes risk, the potential for such a connection exists, warranting further investigation." (PMID 39438007, 2024).
tumor (1 paper, 2025). "PTPN22 has the most significant multitarget intervention potential, while FAM175B and PROM2 are linked to tumor and inflammation pathways, and the specific interactions of LRRTM4 may guide precision treatment strategies." (PMID 40869128, 2025).
LRRTM4 also shares sentences with these, for which no sentence is quoted: autism (2 papers); schizophrenia (2); autism spectrum disorder (1); Cognitive impairment (1); COVID-19 (1); dyslexia (1); hyperlipidemia (1); lymphoma (1); male infertility (1); mental disorder (1); neuroblastoma (1); Obesity (1); pulmonary embolism (1); renal cell carcinoma (1).